POGZ (pogo transposable element derived with ZNF domain)
Description:
Plays a role in mitotic cell cycle progression and is involved in kinetochore assembly and mitotic sister chromatid cohesion. Probably through its association with CBX5 plays a role in mitotic chromosome segregation by regulating aurora kinase B/AURKB activation and AURKB and CBX5 dissociation from chromosome arms. Promotes the repair of DNA double-strand breaks through the homologous recombination pathway.
Synonyms: KIAA0461; ZNF280E; ZNF635; MRD37; WHSUS; ZNF635m
Tractability: Antibody: its Gene Ontology location is reachable by antibodies, with high confidence. PROTAC: UniProt records ubiquitination sites on it; ubiquitination databases record sites on it; its protein half-life has been measured.
Gene: Protein-coding gene on chromosome 1 (151,402,724 to 151,459,494, reverse strand). Ensembl gene ENSG00000143442.
Subcellular location: Nucleus; Chromosome; Cytoplasm
Subcellular location (Human Protein Atlas): Nucleoplasm; Basal body; Cytosol; Plasma membrane
Gene Ontology:
Molecular function: protein binding; DNA-binding transcription factor activity; transcription cis-regulatory region binding; nucleic acid binding
Biological process: double-strand break repair via homologous recombination; kinetochore assembly; mitotic sister chromatid cohesion; regulation of DNA-templated transcription
Cellular component: chromatin; cytoplasm; cytosol; nucleoplasm; nucleus; chromosome
Genetic constraint (gnomAD): Loss-of-function variants: 14 observed, 110.69 expected, observed/expected ratio (o/e) 0.13, 90% interval 0.083 to 0.2. The upper end of that interval is the gene's LOEUF score, 0.2, which puts it in group 1 of 6, group 1 being the genes least tolerant of losing a copy. Missense variants: 1,159 observed, 1,615.5 expected, observed/expected ratio (o/e) 0.72, 90% interval 0.68 to 0.75. Synonymous variants: 615 observed, 611.66 expected, observed/expected ratio (o/e) 1.01, 90% interval 0.94 to 1.08.
Gene-disease validity (ClinGen):
ClinGen rates the evidence that POGZ causes each of these diseases.
intellectual disability-microcephaly-strabismus-behavioral abnormalities syndrome (autosomal dominant): Definitive.
Homologues: Orthologues: chimpanzee POGZ (100% identical), pig POGZ (97% identical), macaque POGZ (97% identical), dog POGZ (96% identical), rabbit POGZ (96% identical), guinea pig POGZ (95% identical), mouse Pogz (94% identical), rat Pogz (93% identical), tropical clawed frog pogz (63% identical). Paralogues in human: TIGD1 (7% identical), JRKL (6% identical), JRK (6% identical), TIGD5 (6% identical), TIGD2 (6% identical), TIGD7 (6% identical), TIGD4 (5% identical), TIGD6 (5% identical), POGK (5% identical), CENPB (5% identical), TIGD3 (4% identical).